LINC00467 (long independently transcribed non-coding RNA 467)
Synonyms: MGC14801; ASAP; C1orf97
Gene: Long non-coding RNA gene on chromosome 1 (211,382,727 to 211,435,570, forward strand). Ensembl gene ENSG00000153363.
Diseases named in the same sentence as LINC00467 in open-access papers:
LINC00467 is named in the same sentence as 27 diseases in open-access papers, as found by Europe PMC text mining. Sharing a sentence is not in itself a finding about the gene and the disease. The quoted sentences say what the papers report.
colorectal cancer (8 papers, 2019 to 2023). A primary or metastatic malignant neoplasm that affects the colon or rectum. "LINC00467, which encodes the micropeptide ASAP (ATP synthase-associated peptide), promotes colorectal cancer progression by regulating the activity of ATP synthase directly." (PMID 37238181, 2023). "Up-regulation of LINC00467 has been associated with poor prognosis of patients with bladder cancer, breast cancer, colorectal cancer, glioma, lung cancer, osteosarcoma and testicular germ cell tumor." (PMID 36229833, 2022). "LINC00467 level has also been reported to be elevated in colorectal cancer tissues compared with normal colon mucosal counterparts." (PMID 36229833, 2022). "One of our published studies and other studies also found LINC00467 to be the biomarker for the metastasis and recurrence of lung cancer, colorectal cancer, and glioma." (PMID 34956437, 2021). "For instance, lncRNA linc00467 could encode an uncharacterized 94‐amino acid (94‐aa) ATP synthase–associated peptide (ASAP), which facilitated colorectal carcinoma cell proliferation in vitro and colorectal carcinoma xenograft tumor growth in vivo." (PMID 36965032, 2023).
glioma (8 papers, 2020 to 2022). A benign or malignant brain and spinal cord tumor that arises from glial cells (astrocytes, oligodendrocytes, ependymal cells). "Using bioinformatics analysis, RT-PCR, and dual luciferase reporter gene assay, the potential role of the LINC00467/miR-339-3p/IP6K2 regulatory axis in glioma was verified." (PMID 35156508, 2022). "Our previous study revealed that LINC00467 is distributed in the nucleus and cytoplasm of glioma cells." (PMID 35156508, 2022). "First, we detected the expression of LINC00467 in glioma tissues and found that the expression of LINC00467 in glioma tissues was significantly higher." (PMID 35156508, 2022). "LINC00467 expression is aberrantly upregulated in multiple tumor tissues and can enhance cell proliferation in neuroblastoma, lung cancer, and glioma cells." (PMID 34094954, 2021). "To investigate the expression of LINC00467 in human glioma, we searched the Cancer Genome Atlas (TCGA) database and found that the LINC00467 expression was significantly elevated in glioma tissues compared with normal tissue." (PMID 32226508, 2020). "Of note, LINC00467 knockdown diminished glioma U87 and U251 cell malignant properties." (PMID 35549646, 2022). "LINC00467 is also distributed in the cytoplasm of glioma cells, suggesting that LINC00467 may play an important supervisory role at the post-transcriptional level." (PMID 35156508, 2022). "In previous studies, we discovered that LINC00467 is significantly upregulated in glioma tissues, and the results of our in vitro cell experiments proved that LINC00467 could significantly facilitate glioma cell proliferation, migration, and invasion." (PMID 35156508, 2022). "We found that LINC00467 was mainly distributed in nucleus of glioma cells, which indicated that LINC00467 might play its regulatory role at the transcriptional level." (PMID 32226508, 2020). "However, the functional roles and potential mechanism of LINC00467 in glioma tumorigenesis remain unknown." (PMID 32226508, 2020). "Hence, we performed experiments and found that LINC00467 mainly located in nucleus of glioma cells, which meant that LINC00467 might play its function at the transcriptional level." (PMID 32226508, 2020). "We then conducted EdU and Transwell experiments to measure the effect of the LINC00467/miR-339-3p/IP6K2 regulatory axis on the proliferation, migration, and invasion of glioma cells." (PMID 35156508, 2022). "Further bioinformatics analysis and in vitro assays revealed that LINC00467 could promote IP6K2 expression by binding to miR-339-3p and promote the malignant progression of glioma." (PMID 35156508, 2022).
breast carcinoma (7 papers, 2017 to 2023). "High level of LINC00467 was positively associated with poor prognosis of breast cancer patients." (PMID 33996559, 2021). "Hence, these data suggested LINC00467 expression was increased in breast cancer and the upregulation of LINC00467 was associated with poor prognosis." (PMID 33996559, 2021). "Moreover, LINC00467 expression in breast cancer has been associated with immune infiltration." (PMID 36229833, 2022). "We then analyzed expression of LINC00467 in 113 normal breast tissues and 1,091 breast cancer samples from the TCGA datasets, which indicated LINC00467 was significantly overexpressed in breast cancer tissues as compared with their normal counterparts." (PMID 33996559, 2021). "Expression level of LINC00467 was higher in breast cancer cells and tissues as compared with normal counterparts, respectively." (PMID 33996559, 2021). "Nevertheless, the expression pattern and functional role of LINC00467 in breast cancer has been less explored." (PMID 33996559, 2021). "Endogenous miR-138-5p levels were increased in LINC00467 silenced breast cancer cells, and decreased with the ectopic expression of LINC00467." (PMID 33996559, 2021). "Additionally, another study by our team demonstrated that LINC00467 is influenced by copy number amplification and DNA demethylation, making it a potential biomarker for breast cancer diagnosis and prognosis." (PMID 37078359, 2023). "Thereby, LINC00467 may serve as a potential therapeutic target in breast cancers." (PMID 33996559, 2021). "Silence of LINC00467 suppressed proliferation, migration, invasion and epithelial-to-mesenchymal transition (EMT) of breast cancer cells in vitro, whereas forced expression of LINC00467 exhibited the opposite effects." (PMID 33996559, 2021). "In the current study, we firstly reported that LINC00467 promoted proliferation, migration, invasion and EMT of breast cancer cells in vitro as well as tumor growth and lung metastasis in Balb/c nude mice." (PMID 33996559, 2021). "In this study, we selected four lncRNAs which had expression alterations ranging from 12% to 20% in breast carcinoma, including PVT1, linc00467, SNHG6, linc00657." (PMID 28938549, 2017). "Despite it has been previously reported the oncogenic role in multiple cancer types, the expression pattern and functional mechanism of LINC00467 in breast cancer has never been investigated." (PMID 33996559, 2021).
lung adenocarcinoma (6 papers, 2021 to 2022). A carcinoma that arises from the lung and is characterized by the presence of malignant glandular epithelial cells. "Linc00467 was highly expressed in lung adenocarcinoma and plays a promotional role in tumorigenesis through dickkopf WNT signaling pathway inhibitor 1 knockdown to activate Wnt/β-catenin axis." (PMID 34713767, 2021). "Numerous studies indicated LINC00467 acted as an oncogene in colorectal cancer, lung adenocarcinoma, hepatocellular carcinoma, glioma, head and neck squamous cell carcinoma and acute myeloid leukemia." (PMID 33996559, 2021). "To explore the mechanisms underlying LINC00467 upregulation in LUAD, we retrieved online sequencing data from the TCGA LUAD cohort (Lung Adenocarcinoma TCGA PanCancer), which comprised of 566 patients." (PMID 35095769, 2021). "It was also demonstrated that the expression of linc00467 was elevated in lung adenocarcinoma tissues and cell lines, involved in tumorigenesis." (PMID 34713767, 2021). "Also, another work clarified that ectopic expression of LINC00467 accelerated the malignant properties of lung adenocarcinoma cells." (PMID 35549646, 2022). "In addition, STAT1-induced upregulation of LINC00467 promotes the proliferation and migration of lung adenocarcinoma cells by epigenetically silencing DKK1 to activate Wnt/beta-catenin signaling pathway." (PMID 33996559, 2021). "Several initiated signaling pathways, including linc00467/miR-20b-5p/cyclin D1 pathway and STAT1-induced upregulation of linc00467 promoted lung adenocarcinoma progression through epigenetically suppressing dickkopf WNT signaling pathway inhibitor 1 to activate Wnt/β-catenin signaling." (PMID 34713767, 2021).
lung carcinoma (6 papers, 2017 to 2022). "Taken together, these results indicate that LINC00467 acts as an oncogene in lung cancer and could represent a novel biomarker for its diagnosis, treatment, and prognosis." (PMID 36203193, 2022).
gastric cancer (4 papers, 2020 to 2022). A primary or metastatic malignant neoplasm involving the stomach. "For instance, LINC00467 was highly expressed in gastric cancer and drove the malignant progression of gastric cancer through the miR-27b-3p/STAT3 axis." (PMID 35587748, 2022).
prostate carcinoma (4 papers, 2021 to 2024). A carcinoma that arises from epithelial cells of the prostate gland. "These facts make LINC00467 a promising therapeutic target for patients with early stage prostate cancer." (PMID 38790894, 2024). "In our study, the GTEx and TCGA databases screening and analysis showed that LINC00467 was overexpressed in most human cancers, including prostate cancer." (PMID 34094954, 2021). "Rescue experiments confirmed that STAT3 is involved in the regulation of miR-494-3p to inhibit the progression of prostate cancer, and miR-494-3p participates in the modulation of LINC00467 to promote the progression of prostate cancer." (PMID 34094954, 2021). "One study investigated the expression of LINC00467 in prostate cancer tissues and cells using Western blot analysis and reverse-transcriptase PCR (RT-qPCR), and they determined that the expression of LINC00467 was upregulated in prostate cancer tissues and cells." (PMID 39655078, 2024). "Increased expression levels of LINC00467 have also been detected in prostate cancer tissue." (PMID 38790894, 2024). "LINC00467 served as an oncogene in prostate cancer progression." (PMID 34094954, 2021). "To investigate whether LINC00467 participates in the progression of prostate cancer in vivo, we used lentivirus to construct a stable strain LINC00467-knockdown DU145 cells and implanted these cells in nude mice to induce subcutaneous tumor formation." (PMID 34094954, 2021). "Hence, inhibiting LINC00467 could be a prospective therapeutic target for patients with early stage prostate cancer." (PMID 34094954, 2021). "Most notably, LINC00467 has been shown to increase EMT in breast, cervical, colorectal, head and neck and prostate cancer as well as osteosarcoma." (PMID 36229833, 2022).
head and neck squamous cell carcinoma (3 papers, 2020 to 2022). A squamous cell carcinoma that arises from any of the following anatomic sites: lip and oral cavity, nasal cavity, paranasal sinuses, pharynx, larynx, and salivary glands. "LINC00467 is activated in HNSCC (head and neck squamous cell carcinoma) cells (HN6, SCC25, HN4, Cal27, SCC4), and silencing LINC00467 inhibited the growth, migration, and EMT process of HNSCC cells." (PMID 32848755, 2020).
hepatocellular carcinoma (3 papers, 2022). A malignant tumor that arises from hepatocytes. "This function of LINC00467 has been verified in hepatocellular carcinoma cells where its silencing has enhanced sensitivity to Axitinib (." (PMID 36229833, 2022).
non-small cell lung carcinoma (3 papers, 2021 to 2022). A group of at least three distinct histological types of lung cancer, including non-small cell squamous cell carcinoma, adenocarcinoma, and large cell carcinoma. "LINC00467 is significantly upregulated in non-small cell lung cancer, promotes tumor cell growth and metastasis, and is related to clinical stage and poor prognosis." (PMID 35303965, 2022). "Also, LINC00467 was upregulated in non-small cell lung cancer tissues." (PMID 35549646, 2022).
bladder cancer (2 papers, 2021 to 2022). "The present study aimed to explore the role of LINC00467 in bladder cancer and its possible underlying molecular mechanisms." (PMID 34123804, 2021). "LINC00467 is highly expressed in bladder cancer and can promote the progression of bladder cancer by regulating the NF-κB signaling pathway." (PMID 34123804, 2021). "In summary, LINC00467 regulates the proliferation and invasion of bladder cancer through the NF-κB signaling pathway." (PMID 34123804, 2021). "We found that LINC00467 plays a critical role in promoting the proliferation and invasion of bladder cancer in vivo and in vitro, suggesting that LINC00467 is likely to function as an oncogene in bladder cancer." (PMID 34123804, 2021). "LINC00467 can activate the NF-κB signaling pathway to promote the occurrence and development of bladder cancer, and can be used as a potential target for bladder cancer treatment, thus providing new ideas for targeted therapy of bladder cancer." (PMID 34123804, 2021). "RIP, RNA pulldown, and CO-IP were used to demonstrate the potential mechanism by which LINC00467 regulates the progression of bladder cancer." (PMID 34123804, 2021). "To determine the molecular mechanism by which LINC00467 promotes bladder cancer cell proliferation and invasion, we analyzed its localization in cells and found that LINC00467 is located both inside the nucleus and the cytoplasm." (PMID 34123804, 2021). "Therefore, targeting LINC00467 is very likely to provide a new strategy for the treatment of bladder cancer and for improving patient prognosis." (PMID 34123804, 2021). "Therefore, we propose that LINC00467 regulates the proliferation and invasion of bladder cancer through the NF-κB signaling pathway." (PMID 34123804, 2021). "LINC00467 is highly expressed in bladder cancer tissues and can function as an oncogene." (PMID 34123804, 2021). "Assessment of expression data from a GEO dataset and the TCGA database has revealed up-regulation of LINC00467 in bladder cancer samples and negative correlation between its expression and patients’ prognosis." (PMID 36229833, 2022). "Compared to the negative control group, in the LINC00467 overexpression + CAPE group, the proliferation ability of bladder cancer cells was markedly reduced; however, opposite results were obtained in the LINC00467 overexpression group." (PMID 34123804, 2021).
neuroblastoma (2 papers, 2014 to 2021). Neuroblastoma (NB) is the most common solid, extracranial childhood tumor. "This study reveals that knocking-down linc00467 gene expression reduces the number of viable neuroblastoma cells, increases the percentage of cells at sub-G1 phase of the cell cycle and induces apoptosis in neuroblastoma cells." (PMID 24586304, 2014). "While linc00467 had not been studied at all in the literature, we discovered that linc00467 suppressed the expression of its downstream protein-coding gene RD3, and induced neuroblastoma cell survival by reducing the expression of the tumour suppressor gene DKK1." (PMID 24586304, 2014).
osteosarcoma (2 papers, 2022). A usually aggressive malignant bone-forming mesenchymal neoplasm, predominantly affecting adolescents and young adults. "Additionally, overexpression of LINC00467 has been observed in osteosarcoma tissues and cells." (PMID 35549646, 2022).
Leber congenital amaurosis type 12 (1 paper, 2014). "In this study, we have confirmed that knocking-down linc00467 up-regulates the expression of its neighbouring protein-coding gene RD3, which encodes a retinal protein responsible for the retinal degeneration disorder Leber congenital amaurosis type 12." (PMID 24586304, 2014).
melanoma (1 paper, 2023). A malignant, usually aggressive tumor composed of atypical, neoplastic melanocytes. "Differential level of LINC00467 in melanoma tissues and its prognostic value were analyzed in GEPIA, which were further confirmed in clinical samples we collected." (PMID 36987414, 2023). "EdU assay uncovered that overexpression of LINC00467 enhanced EdU-stained cell ratio in melanoma cells, which was reduced, conversely, by knockdown of LINC00467." (PMID 36987414, 2023). "Therefore, LINC00467 served as an oncogene in melanoma process." (PMID 36987414, 2023).
sarcoma (1 paper, 2022). A usually aggressive malignant neoplasm of the soft tissue or bone. "Many studies have verified that LINC00467 is highly expressed in a variety of carcinoma and sarcoma tissues and cells." (PMID 36203193, 2022).